GFAP (glial fibrillary acidic protein)
Diseases named in the same sentence as GFAP in open-access papers (continued):
Sharing a sentence is not in itself a finding about the gene and the disease.
ganglioglioma (4 papers, 2018 to 2022). A well differentiated, slow growing neuroepithelial neoplasm composed of neoplastic, mature ganglion cells and neoplastic glial cells. "Gangliogliomas are uncommon intracranial tumors that include neoplastic and abnormal ganglion cells, and show positive immunohistochemical staining for GFAP and syn." (PMID 36548530, 2022). "One patient with a ganglioglioma was found to express intense GFAP staining on histology and was eventually excluded from analysis." (PMID 32588294, 2020).
glioneuronal tumors (4 papers, 2018 to 2025). "Looking in a supervised way at expression of particular differentiation markers commonly used for immunohistochemical analysis of glial/glioneuronal tumors, we found low GFAP expression, and modest levels of OLIG2, NeuN (RBFOX3), MAP2 and synaptophysin (SYP)." (PMID 34417833, 2021).
Hyponatremia (4 papers, 2021 to 2026). An abnormally decreased sodium concentration in the blood. "Manifestations of intractable hyponatremia and hypokalemia in autoimmune glial fibrillary acidic protein (GFAP) astrocytopathy have been rarely reported." (PMID 33504323, 2021).
Intellectual disability (4 papers, 2021 to 2026). "NFIB (nuclear factor I/B) too is associated with intellectual disability and acts as a transcription activator of GFAP, which is found to be significantly upregulated in all AD stages in this work and is also essential for proper brain development." (PMID 39299805, 2024).
Intraventricular hemorrhage (4 papers, 2020 to 2024). Bleeding into the ventricles of the brain. "The authors even describe one case where a small intraventricular hemorrhage near the sublingual gyrus was missed on CT but present on MRI and was associated with a marked increase in GFAP levels that persisted across the 24 h sampling period (median 4.61 ng/mL)." (PMID 32098419, 2020).
lung carcinoma (4 papers, 2019 to 2024). "In an in vivo experimental model using human lung cancer-derived (HARA-B) cells in nude mice, a significant increase in glial fibrillary acidic protein (GFAP)-positive astrocytes around metastatic lesions was detected." (PMID 37190188, 2023).
microcephaly (4 papers, 2011 to 2017). A congenital or acquired developmental disorder in which the circumference of the head is smaller than normal for the person's age and sex. "Understanding the phosphorylation status of GFAP in differentiated neuroprogenitor cells during Zika virus-associated microcephaly would be an important follow-up for further understanding neuronal disease progression." (PMID 29022904, 2017). "We previously reported that GFAP-SCAP mutant mice have microcephaly without changes in neuronal and astrocyte density." (PMID 28549068, 2017).
motor neuron disease (4 papers, 2011 to 2024). "As expected, we found that elevation of NFL and GFAP was also associated with neurodegenerative disorders, with strong effects seen for Parkinson's and motor neuron disease." (PMID 38282238, 2024). "The effect of NF-κB deficiency in glial cells on severity of motor neuron disease was examined using cohorts of GFAP-IκBαAA (indicated as Tg), SOD1G93A (indicated as G93A) and GFAP-IκBαAA/SOD1G93A (indicated as double Tg) transgenic mice." (PMID 21445241, 2011). "Immunohistochemical analysis of spinal cord sections revealed that motor neuron disease following SNI was associated with increased microglial (Iba1) and astrocytic (GFAP) response in the ventral horn of the spinal cord, indicative of reactive gliosis." (PMID 27028103, 2016).
paraganglioma (4 papers, 2016 to 2025). A benign or malignant neoplasm arising from paraganglia located along the sympathetic or parasympathetic nerves. "Ependymal cells are GFAP positive, while neoplastic cells of paraganglioma are GFAP negative." (PMID 34307231, 2021). "GFAP staining can be used to help differentiate the two pathologies because ependymal cells are GFAP positive whereas GFAP staining is negative in neoplastic cells of paragangliomas." (PMID 27433367, 2016).
periventricular leukomalacia (4 papers, 2015 to 2022). Periventricular leukomalacia (PVL) is a brain injury disorder characterized by the death of the white matter of the brain due to softening of the brain tissue. "Periventricular leukomalacia (PVL) is associated with increased GFAP-positive astrocytes in the WM of neonatal brains." (PMID 26251894, 2015). "There was a strongly positive glial fibrillary acidic protein signal and no striking anoxic changes, giving an overall impression of periventricular leukomalacia." (PMID 32588908, 2020).
primary progressive MS (4 papers, 2018 to 2025). "One of the most promising fluid biomarkers is glial fibrillary acidic protein (GFAP), which reflects astrocytic reactivity and is significantly elevated in the cerebrospinal fluid (CSF) and serum of patients with secondary and primary progressive MS." (PMID 41009385, 2025).
Retinal dystrophy (4 papers, 2012 to 2025). Retinal dystrophy is an abnormality of the retina associated with a hereditary process. "Glial fibrillary acidic protein (GFAP) is the main intermediate filament protein in mature astrocytes, but it is often expressed in Muller cells in response to retinal injuries and the degenerative changes associated with genetically-mediated retinal dystrophy." (PMID 26091175, 2015). "In contrast, in Royal College of Surgeons (RCS) rats with inherited retinal dystrophy, RPE transplantation significantly reduced GFAP expression in Müller cells and stabilized Müller cell activity." (PMID 22715395, 2012).
sarcoidosis (4 papers, 2022 to 2025). Sarcoidosis is a multisystemic disorder of unknown cause characterized by the formation of immune granulomas in involved organs. "There is ongoing discussion regarding whether SLIPPERS is a disease entity on its own or just an acronym encompassing many underlying diagnoses, such as sarcoidosis, vasculitis and anti-glial fibrillary acidic protein (GFAP)-associated disease." (PMID 37626547, 2023).
sarcoma (4 papers, 2014 to 2024). A usually aggressive malignant neoplasm of the soft tissue or bone. "The distinct diagnostic features for these tumors included positive GFAP and Olig-2 expression, negativity of WT-1 and reticulin, and a methylation profile incompatible with conventional MC CIC-rearranged sarcomas." (PMID 38926750, 2024). "The combination of GFAP, Olig-2, synaptophysin, WT-1 and reticulin staining can help differentiate sarcoma and neuroepithelial tumors." (PMID 38926750, 2024). "As noted, we observed an obvious elevation in the spinal expressions of IL-17, CXCL1 and GFAP in the animals 7 days after sarcoma cell implantation using an ELISA assay (p < 0.05, n = 4)." (PMID 36672133, 2023). "The biphasic pattern is confirmed by reticulin fibers that highlight the reticulin-rich sarcoma component and glial fibrillary acidic protein (GFAP) positivity in immunohistochemistry, which demonstrates the glial component." (PMID 25580128, 2014). "Here, we first reported the spinal rise in IL-17 secretion, CXCL1 release and GFAP expression in mice with peripheral nerve trauma and sarcoma implantation, consistent with nociceptive behaviors of long-lasting mechanical allodynia as well as heat hyperalgesia." (PMID 36672133, 2023). "Interestingly, repetitive pre-administration of RvD2 (i.t., 500 ng) suppressed the overexpression of IL-17, CXCL1 as well as GFAP proteins in the dorsal horn following sarcoma exposure (p < 0.05, n = 4)." (PMID 36672133, 2023).
Senile plaques (4 papers, 2018 to 2023). Senile plaques are extracellular deposits of amyloid in the gray matter of the brain. "Astrocytes, when associated with senile plaques, become reactive with morphological hypertrophy manifested by thicker processes and increased expression of the intermediate filament proteins glial fibrillary acidic protein (GFAP), vimentin, nestin and synemin." (PMID 33806259, 2021). "Furthermore, GFAP-positive reactive glial cells were detected in close proximity to Aβ-positive senile plaques." (PMID 38042775, 2023). "The intensity of GFAP and the coverage of BSB-stained senile plaques in the cortex were comparable in HFD and NCD AD mice at the age of 9.5 months." (PMID 30096853, 2018). "GFAP or Iba-1 and Aβ were stained with double-labeled immunofluorescence, and we found that ECH could significantly inhibit the activation of glial cells around senile plaques." (PMID 35665898, 2022).
spinal cord injury (4 papers, 2013 to 2024). Penetrating and non-penetrating injuries to the spinal cord resulting from traumatic external forces (e.g., WOUNDS, GUNSHOT; WHIPLASH INJURIES; etc.). "Typical biomarkers such as glial fibrillary acidic protein (GFAP), neurofilaments, cleaved tau, myelin basic protein, neuron-specific enolase (NSE), and S100b are elevated after traumatic spinal cord injuries." (PMID 39703513, 2024).
transient cerebral ischemia (4 papers, 2010 to 2025). "Double-staining for AQP4 and GFAP was performed to assess the functional changes induced by transient cerebral ischemia-reperfusion and sildenafil treatment in the hippocampus by BBB disruption." (PMID 39335590, 2024).
tuberous sclerosis (4 papers, 2021 to 2025). Hereditary disease characterized by seizures, intellectual disability, developmental delay, and skin and ocular lesions. "The GFAP immunolabelling of neurons in patients suffering from AD or tuberous sclerosis highlights that immunopositivity for GFAP in neurons is not TBI-specific." (PMID 34114049, 2021).
vasculitis (4 papers, 2020 to 2024). "In conclusion, we present the first case of biopsy proven SV-cPACNS vasculitis with associated positive GFAP CSF antibodies." (PMID 36737749, 2023). "We present the first case of biopsy proven SV-cPACNS vasculitis associated with an incidental finding of CSF GFAP antibodies." (PMID 36737749, 2023). "This study is the first to demonstrate that serum GFAP at diagnosis can predict cross-sectional vasculitis activity by reflecting the extent of renal involvement in patients with AAV." (PMID 39459426, 2024). "In the small number of brain biopsies performed in adult patients with GFAP astrocytopathy, histopathology demonstrated lymphocytic perivascular inflammation, a distinctly different inflammatory pattern from that of true vasculitis." (PMID 36737749, 2023). "In this study, we explored whether serum GFAP could be used to estimate cross-sectional vasculitis activity as measured by BVAS in patients with AAV, and we obtained several noteworthy findings." (PMID 39459426, 2024). "Future research on GFAP could focus on its ability to track disease progression in vasculitis, its broader utility across different forms of vasculitis, and its potential as a predictor of therapeutic response." (PMID 39459426, 2024). "This study investigated whether serum GFAP could be used to estimate cross-sectional vasculitis activity presented via the Birmingham vasculitis activity score (BVAS) in patients with antineutrophil cytoplasmic antibody-associated vasculitis (AAV)." (PMID 39459426, 2024). "For example, suppression of astrogliosis in glial fibrillary acidic protein (GFAP) knockout mice substantially facilitates the penetration of Staphylococcus aureus or Toxoplasma gondii into the brain, which results in vasculitis, purulent ventriculitis and severe brain oedema." (PMID 33304243, 2020). "Therefore, this study aims to explore whether serum GFAP can serve as a reliable biomarker for assessing cross-sectional vasculitis activity in AAV patients, with the goal of enhancing both objectivity and convenience in clinical evaluations." (PMID 39459426, 2024).
acute liver failure (3 papers, 2021 to 2024). Rapid deterioration of liver function causing encephalopathy and coagulopathy. "Another study revealed loss of GFAP expression in postmortem cerebral tissues from HE patients who died as a result of brain herniation due to acute liver failure." (PMID 39556255, 2024). "Acute liver failure has been found to damage the genes expressing glial fibrillary acidic protein (GFAP), which participates in the mobility and structure and provides structural stability." (PMID 33584185, 2021). "A previous study showed that the reduction in GFAP after acute liver failure was involved in astrocyte swelling, and significant decrease or increase in GFAP was also observed in the brain regions, such as hippocampus and cerebral cortex, from diabetic animals." (PMID 33466498, 2021).
Alpers syndrome (3 papers, 2023 to 2025). A cerebral degeneration that results in progressive degeneration of grey matter in the cerebrum and has_symptom convulsions. "Additionally, the overexpression of SOX2-positive neural progenitors and an increased number of GFAP-positive astrocytes point towards astrogliosis in the context of cortical neuronal loss, a hallmark of brain pathology in Alpers' syndrome." (PMID 38385069, 2024). "Comparison of PMD patient tissues revealed a striking increase in GFAP and HLA-DR immunoreactivity localised to the focal lesions in tissues from the patients with Alpers’ syndrome." (PMID 40445405, 2025). "Since reactive astrocytes from Alpers’ syndrome patient occipital tissues frequently appeared enlarged, the size of GFAP + astrocytes identified using immunofluorescence were measured to confirm this visual observation." (PMID 37259148, 2023). "As a comparison, we also phenotypically characterised GFAP + astrocytes in frontal cortical tissues where neurodegeneration and gliosis are typically less severe in Alpers’ syndrome." (PMID 37259148, 2023). "Most occipital cortex tissues from patients with Alpers’ syndrome showed a visible increase in GFAP + labelling relative to control tissues, including an apparent increased density and intensity of GFAP + cells." (PMID 37259148, 2023). "Our qualitative observations of reactive astrogliosis in the occipital cortex were confirmed by a higher mean percentage area of GFAP + labelling in seven of ten patients with Alpers’ syndrome relative to controls (P < 0.05)." (PMID 37259148, 2023). "Immunohistochemistry to identify glial fibrillary acidic protein (GFAP)-reactive astrocytes revealed striking reactive astrogliosis localised to the primary visual cortex of Alpers’ syndrome tissues, characterised by abnormal-appearing hypertrophic astrocytes." (PMID 37259148, 2023). "Finally, it is recognised that anti-GFAP antibodies only label a subset of astrocytes, however, the limited tissue availability prevented the inclusion of additional markers to identify individual astrocytes, albeit the majority of Alpers’ syndrome patient astrocytes were GFAP+." (PMID 37259148, 2023).
Alpha-thalassemia (3 papers, 2022 to 2026). Alpha-thalassemia is an inherited hemoglobinopathy characterized by impaired synthesis of alpha-globin chains leading to a variable clinical picture depending on the number of affected alleles. "In addition to histone H3K27M mutation, immunohistochemical staining showed that the tumor cells were positive for glial fibrillary acidic protein, oligodendrocyte transcription factor 2, alpha-thalassemia/mental retardation syndrome X, S-100 and Vimentin." (PMID 35713454, 2022). "Immunohistochemical staining revealed that the tumor cells were positive for GFAP, oligodendrocyte transcription factor 2, histone H3K27M mutant protein, alpha-thalassemia/mental retardation syndrome X, S-100 and Vimentin, but negative for IDH1 R132H, Syn and NeuN." (PMID 35713454, 2022).
anxiety disorder (3 papers, 2024 to 2025). A category of psychiatric disorders which are characterized by anxious feelings or fear often accompanied by physical symptoms associated with anxiety. "Serum glial fibrillary acidic protein (GFAP), a peripheral biomarker of astrocyte activation, has been shown to both reflect the degree of astrocyte-mediated neuroinflammation and correlate with the pathogenesis of anxiety disorders." (PMID 41210138, 2025).
bacterial meningitis (3 papers, 2011 to 2017). Inflammation of the membranes surrounding the brain and spinal cord due to a bacterial infection. "In order to validate our previous in vitro findings in vivo, we used double fluorescence microscopy with receptor specific antibodies to examine the localization of MARCO and GFAP in astrocytes from infant rats with bacterial meningitis with NM or SP." (PMID 21299846, 2011).
Behçet's disease (3 papers, 2020 to 2025). "It is unclear if GFAP is another autoantigen in Behcet’s syndrome; therefore, further studies are warranted." (PMID 37101204, 2023). "Leptomeningeal involvement is not reported for vitamin B12 deficiency and PML-IRIS, but if this imaging feature is present, Susac’s syndrome, Behçet’s disease, PACNS, ECD and GFAP meningoencephalomyelitis should also be maintained in the differential diagnosis." (PMID 31925469, 2020).
cerebellar tumors (3 papers, 2020 to 2024). "Additional CNS HGNET-BCOR cerebellar tumor, originally diagnosed as unclassified malignant neuroepithelial tumor, showed lack of exon 15 of BCOR gene duplication and negative reaction for GFAP and synaptophysin." (PMID 32650833, 2020).
cerebral microbleeds (3 papers, 2023 to 2025). Cerebral microbleeds are a group of pathological processes affecting the small arteries, arterioles, capillaries and venules of the brain, as detected by brain imaging techniques. "Additionally, lobar cerebral microbleeds, in combination with phosphorylated tau-217 or glial fibrillary acidic protein, were synergistically associated with cognitive changes." (PMID 40343697, 2025). "Therefore, we evaluated the associations of plasma NfL, GFAP, and t-tau to SVD markers, including white matter hyperintensity volume (WMHV), subcortical infarcts, cerebral microbleeds, and large perivascular spaces in a large population-based cohort." (PMID 37530894, 2024). "Moreover, sGFAP levels did not significantly differ between patients with presence of cerebral microbleeds (median GFAP: 207.8 vs. 185.8 pg/ml, p = 0.65) or lacunes (median sGFAP: 175.5 vs. 187.2 pg/ml, p = 0.86), compared to those without these lesions." (PMID 36056929, 2023).
choroid plexus papilloma (3 papers, 2016 to 2024). "A focal distribution of GFAP is observed in 25% to 55% of choroid plexus papillomas and 20% of choroid plexus carcinomas." (PMID 32756190, 2020). "Furthermore, the rough hobnail appearance of a choroid plexus papilloma coupled with a lack of extensive glial fibrillary acidic protein immunoreactivity holds value in further differentiating the two tumors." (PMID 39768979, 2024).
eosinophilia (3 papers, 2019 to 2025). "The immunohistological investigations showed an increased glial reaction, increased eosinophilia, and a higher GFAP activity in the retinal tissue beneath the implanted device." (PMID 34641889, 2021). "However, immunohistological investigations showed an increased glial reaction, increased eosinophilia, and GFAP activity in the retinal tissue beneath the implanted device." (PMID 34641889, 2021).